ZNF217 (zinc finger protein 217)
Diseases named in the same sentence as ZNF217 in open-access papers (continued):
Sharing a sentence is not in itself a finding about the gene and the disease.
cancer (59 papers, 2007 to 2026). A tumor composed of atypical neoplastic, often pleomorphic cells that invade other tissues. "Evidence suggests that ZNF217 fine tunes a variety of molecular signaling pathways to reprogram integrated circuits governing hallmark capabilities within cancer cells." (PMID 36551531, 2022). "Extensive data show that high ZNF217 expression levels are associated with poor prognosis in several human cancers and predictive of response to chemotherapy or endocrine therapy (for reviews)." (PMID 36551531, 2022). "The ZNF217 locus is located within the 20q13 region, a region frequently amplified in human cancers, and amplification at ZNF217 locus has been associated with poor prognosis in some reports." (PMID 36551531, 2022). "The ZNF217 oncogene promotes progression, pluripotency and resistance to therapy in different types of cancer and is associated with increased risk of metastasis." (PMID 36551531, 2022). "Although few ZNF217 direct target genes have been formally validated, those genes encode for key masters of tumor progression and cancer cell plasticity." (PMID 36551531, 2022). "Aberrant high expression levels of ZNF217 have been associated with poor prognosis in several human cancers." (PMID 36551531, 2022). "The oncogenic transcription factor ZNF217 orchestrates several molecular signaling networks to reprogram integrated circuits governing hallmark capabilities within cancer cells." (PMID 36551531, 2022). "Since then, ZNF217 has been implicated in ovarian and other cancer types, where it has been linked to diverse oncogenic phenotypes including cell proliferation, survival, and invasion." (PMID 28212443, 2017). "The ZNF217 gene belongs to the 20q13 region, a region frequently amplified in human cancers and importantly, ZNF217 protein interferes and cooperates with proteins encoded by other genes present in this region (AURKA, BCL2L1, eEF1A2)." (PMID 26431164, 2015). "Several studies show that overexpression of ZNF217 in several cancers is associated with poor prognosis." (PMID 26675567, 2015). "ZNF217 cooperates with several intracellular signaling networks to reprogram integrated circuits governing hallmark capabilities within cancer cells." (PMID 26431164, 2015). "For example, ZNF217 (encoding zinc finger protein 217) is an important oncogene in many cancer types and its overexpression has been implicated in cell immortalization and resistance to chemotherapy." (PMID 21156036, 2010). "The three non-imprinted genes at 20q11-q13.32 examined in our study, AURKA, MYBL2, and ZNF217, have a strong influence on cell cycle, proliferation, signaling, survival, and differentiation of malignant cells and on cancer progression, and they have been implicated in cancer drug resistance." (PMID 36461044, 2022). "Interestingly, both the list of 1,230 ZNF217-bound differentially regulated genes and the list of 854 ZNF217-ERα co-bound differentially regulated genes show strong associations with genes associated with multiple cancer studies present in the Molecular Signatures Database (MSigDB)." (PMID 24962896, 2014). "By regulating a broad range of critical processes intrinsic to a cancer cell, ZNF217 can impact multiple stages of tumor progression." (PMID 41345234, 2025). "ZNF217 amplification and overexpression are common occurrences in these malignancies, where it has been shown to promote cancer cell proliferation, survival, stemness, immortalization, metastasis, and drug resistance 27, 31, 33-39." (PMID 40093906, 2025). "Background/Objectives: The expression of oncogene zinc-finger protein 217 (ZNF217) has been reported to play a central role in cancer development, resistance, and recurrence." (PMID 39770403, 2024). "Discovering new compounds that can target ZNF217 would help improve the prognosis of patients with cancer." (PMID 39770403, 2024).
cancer (continued). "High levels of ZNF217 expression provide advantages to a specific subset of cancer cells to reprogram tumor progression, drug resistance and cancer cell plasticity." (PMID 36551531, 2022). "While the oncogenic role of ZNF217 in several human cancers is well admitted, few ZNF217-targeting therapeutic options have emerged." (PMID 36551531, 2022). "The zinc-finger protein 217 (ZNF217) is an oncogenic transcription factor (TF) that plays a key role in tumorigenesis, orchestrating tumor progression in several human cancers at both early and late stages." (PMID 36551531, 2022). "This oncogenic effect is independent of the demethylase activity, and depends on the interaction with the ZNF217 protein, classified as an oncogene because of its increased expression in many cancers." (PMID 35406676, 2022). "In fact, studies show that ZNF217 shapes cancer growth through epigenetic mechanisms that promote tumor progression, including DNA methylation, interactions with noncoding RNAs and epitranscriptome refining, which are summarized in this review." (PMID 36551531, 2022). "Altogether, with this topic having been poorly reviewed and appreciated, a better understanding and clear overview of the intricate interplay between ZNF217 and epigenetics networks in cancer is of utmost importance." (PMID 36551531, 2022). "SP-2509 inhibits the viability of cancer cells by blocking the binding of LSD1 to ZNF217 by inhibiting LSD1-independent function in castration-resistant PCa." (PMID 36059955, 2022). "We also discuss the exciting burgeoning translational medicine and candidate therapeutic strategies emerging from those recent findings connecting ZNF217 to epigenetic deregulation in cancer." (PMID 36551531, 2022). "ZNF217 stimulates cancer cell migration, invasion and epithelial–mesenchymal transition (EMT) by negative regulation of CDH1/E-cadherin expression." (PMID 36551531, 2022). "By refining the DNA methylation status at P15INK4B gene; ZNF217, thus, impairs proliferative control in cancer cells." (PMID 36551531, 2022). "To date, the Akt inhibitor triciribine is the only drug shown to counteract the ZNF217-driven deleterious effects in vivo and has been proposed as a clinical strategy to treat ZNF217-positive cancer patients." (PMID 36551531, 2022). "Two main previous reviews have extensively depicted the role of ZNF217 in carcinogenesis by affecting the hallmarks of cancers, emphasizing ZNF217 importance as a prognostic biomarker for early prevention and as a therapeutic target." (PMID 36551531, 2022). "In NSCLC, the positive expression rate of ZNF217 protein was higher in cancer tissues than that in paracancerous tissues, and increased with the increase of TMN stage." (PMID 34195081, 2021). "Zinc finger protein 217 (ZNF217) is protein-coding gene contributing to the tumorigenesis of various human cancers." (PMID 32742190, 2020). "ZNF217 is proved to be a central role in cancer development, and FBXO31 is proved to be a candidate tumor suppressor gene, by generating Skp Cullin F-box containing SCF complex, it causes cell senescence and has consistent tumor suppressor attributes." (PMID 32318558, 2020). "ZNF217, a member of the Krüppel-like family, is a transcription factor that functions as an oncogene in many cancer types." (PMID 31756991, 2019). "Triciribine was the lead drug candidate identified from an in silico screen of ∼50,000 drugs specific for cancer cells that have high expression of ZNF217." (PMID 29312549, 2017). "The rearrangement results in the promoter of another highly-expressed salivary gland gene, PRB3, possibly driving overexpression of ZNF217, a reported oncoprotein in several cancer types." (PMID 28212443, 2017). "ZNF217 has been identified as a target gene that is amplified in circulating cancer cells and is part of a signature that predicts response to therapy." (PMID 29312549, 2017).
cancer (continued). "Aberrant amplification of SALL4 and ZNF217 serve as unfavorable predictors of survival expectancy among cancer sufferers, revealing great potential as targeted spots in future therapeutics." (PMID 27007163, 2016). "In agreement with previous individual studies, we meta-analyzed all relevant cohorts and made a globally first statement that ZNF217 amplification had an implication of worse prognosis in solid malignancies, despite of cancer subtypes or sex predominance." (PMID 27007163, 2016). "Integrative analysis of mRNA and miRNA temporal expression profiles identified miR-503 as the strongest candidate master regulator of the estrogen response, in part through suppression of ZNF217—an oncogene that is frequently amplified in cancer." (PMID 27539783, 2016). "In this review, we focus on recent research on ZNF217-driven molecular functions in human cancers, revisiting major hallmarks of cancer and highlighting the downstream molecular targets and signaling pathways of ZNF217." (PMID 26431164, 2015). "These authors also showed that triciribine inhibits the growth of ZNF217-overexpressing cells in vitro and in vivo, indicating that it is a potential target for the treatment of ZNF217-overexpressing cancers." (PMID 26675567, 2015). "Using in silico and in vitro screening approaches to identify candidate therapeutics able to inhibit growth of cancer cells expressing high ZNF217, triciribine (also known as API-2) was revealed as a good drug candidate." (PMID 26431164, 2015). "This review will also describe the evolving landscape of translational medicine with regards to assessing ZNF217 expression levels (mRNA or protein) as a new prognostic or predictive biomarker for anti-cancer therapies." (PMID 26431164, 2015). "We also discuss the exciting translational medicine investigating ZNF217 expression levels as a new powerful biomarker, and ZNF217 as a candidate target for future anti-cancer therapies." (PMID 26431164, 2015). "In this review, we have extensively documented the implication of ZNF217 in the major hallmarks of cancer, including sustained proliferative signals, growth suppressor evasion, replicative immortality, resistance to cell death and invasion activation." (PMID 26431164, 2015). "The zinc-finger protein 217 (ZNF217) is an oncogenic protein that plays deleterious functions in various human cancers." (PMID 26431164, 2015). "An increasing body of research indicates that ZNF217 interferes with several intracellular signaling networks for reprogramming cancer cells." (PMID 26431164, 2015). "The recently described oncogene ZNF217 belongs to a chromosomal region that is frequently amplified in human cancers." (PMID 26431164, 2015). "Several studies have used gene-expression microarrays to extract gene networks in the vicinity of ZNF217 in a cancer context and all revealed by gene ontology an effect on cell adhesion, cell motility, migration and invasion, of ZNF217 deregulated expression." (PMID 26431164, 2015). "To date, it is the only drug tested in vivo that seems to counteract the ZNF217-driven deleterious effects and has been proposed as a clinical strategy to treat ZNF217+ cancer patients." (PMID 26431164, 2015). "In contrast, only two known cancer genes, ZNF217 and LHFP, were identified among the thirty MBC candidate driver genes." (PMID 24194916, 2013). "Since the AURKA gene is located, like the ZNF217 gene, at 20q13, a region frequently amplified in human cancers, our finding is of particular interest for several reasons." (PMID 21059223, 2010). "It has been reported that ZNF217 expression is significantly higher in CRC cancer tissues than in paraneoplastic tissues and that low expression of ZNF217 in CRC cells may inhibit cell migration and invasiveness." (PMID 40085529, 2025). "Reports show that ZNF217 is deregulated in many cancers and contributes to disease progression." (PMID 41345234, 2025).
cancer (continued). "Aberrant amplification of ZNF217 has been observed in various cancers and precancerous conditions." (PMID 40083704, 2025). "Interestingly, ZNF217 induces metastatic phenotypes in fallopian tube cells, suggesting potential role in the transition of early-stage tumors to aggressive carcinoma." (PMID 41345234, 2025). "Thus, while ZNF217 is expressed by cancer cells of various types, the tested cucurbitacins selectively decreased ZNF217 expression only in the AML cell line OCI-AML3." (PMID 39770403, 2024). "Therefore, targeting ZNF217 has been proposed as a possible strategy to fight cancer, and there has been much research on compounds that can target ZNF217." (PMID 39770403, 2024). "Accordingly, repressing ZNF217 expression inhibits cancer progression." (PMID 36646721, 2023). "Little is known about the function of ZNF217 in cancer today." (PMID 37648814, 2023). "For example, activation of the proto-oncogenes MYC, ZNF217, and WT1 is associated with DEGs expressed by all three tumor types examined in this study, and therapeutic approaches to inhibition of all three in cancers are being developed." (PMID 36099287, 2022). "Deciphering this close interplay between ZNF217 and epigenetic processes, thus, sets the stage for considering epidrugs strategies, alone or in combination with conventional treatments, and holds potent therapeutic potential for the treatment of ZNF217-positive cancers." (PMID 36551531, 2022). "The zinc-finger protein 217 (ZNF217) gene is frequently amplified in human cancers." (PMID 35912186, 2022). "High ZNF217 expression levels are a biomarker of poor prognosis in several cancers." (PMID 36551531, 2022). "Deregulated DNA methylation status at ZNF217 locus or an intricate cross-talk between ZNF217 and noncoding RNA networks could explain aberrant ZNF217 expression levels in a cancer cell context." (PMID 36551531, 2022). "Altogether, miR-205, miR-135, miR-141-3p, MALAT1 and HOXA11-AS may represent a new generation of predictive biomarkers and therapeutic targets in ZNF217-positive cancers prone to developing BM." (PMID 36551531, 2022). "ZNF217 is an oncogene that has deleterious effects in various human cancers." (PMID 34195081, 2021). "An aberrant protein levels of ZNF217 has been reported in many cancer cell lines and may cause unregulated targeting by the CoREST-LSD1 complex, with a profound effect on cancer progression." (PMID 32429325, 2020). "The authors concluded that the mir-200/ZNF217 axis may be the potential therapeutic target in AD and cancer." (PMID 31756991, 2019). "In a larger pan-cancer set of 4128 TCGA exomes with expression profiling, we identified mutational correlation with expression for additional elements (e.g., near GATA3, CDC6, ZNF217, and CTCF transcription factor binding sites)." (PMID 29354286, 2018). "ZNF217 located on chromosome 20q13.2 is frequently amplified in many tumors and cancer cells." (PMID 29069770, 2017). "Recent studies showed that ZNF217 cooperates with several intracellular signaling networks to reprogram integrated circuits governing hall mark capabilities within cancer cells, including cellular immortalization, increased cellular proliferation, resistances to cell death and invasion activation." (PMID 27768596, 2016). "These new findings support the existence of a ZNF217 protein pool of unknown biological function, localized in the cytoplasm of cancer cells." (PMID 26431164, 2015). "ZNF217 has been depicted to impact one of the most fundamental traits of cancer cells involving their ability to sustain chronic proliferation via the deregulation of signals that allow progression through the cell cycle, cell growth and disruption of anti-proliferative signaling." (PMID 26431164, 2015). "Finally, we will discuss the emerging therapeutic strategies to counteract ZNF217 or ZNF217-driven deleterious effects in cancer." (PMID 26431164, 2015).
cancer (continued). "Amplification at the ZNF217 locus has been previously reviewed and linked to poor prognosis in several cancers; however other authors have failed to make this link, likely due to differences in probes and cutoff levels used for amplification evaluation." (PMID 26431164, 2015). "It has been hypothesized that the selective amplification of ZNF217 allows cancer cells to overcome senescence and become immortal, a requirement likely essential for cancer development." (PMID 21059223, 2010). "The precise mechanisms involved in ZNF217 pro-survival function are currently unknown, and utmost importance is given to deciphering the role of ZNF217 in cancer therapy response." (PMID 21059223, 2010). "This study aimed to decipher the contribution of ZNF217 in cancer therapy response and to determine whether ZNF217 is able to counteract apoptotic signals other than those induced by DNA damage stimuli." (PMID 21059223, 2010). "The precise mechanisms involved in ZNF217 pro-survival function are currently unknown, and it is thus of utmost importance to decipher the role of ZNF217 in response to cancer therapy." (PMID 21059223, 2010). "Therefore, targeting the ZNF217 oncogene could be promising not only in terms of treating cancer and its related chemoresistance but also as a potential biomarker for its early diagnosis." (PMID 39770403, 2024). "Therefore, targeting ZNF217 could be a promising strategy to fight cancer and its related chemoresistance." (PMID 39770403, 2024). "ZNF217-driven functions impact several traits of cancer cells involving sustained proliferative signals, evasion from growth suppressors, enabled replicative immortality, resistance to apoptosis, cancer stem cell enrichment, drug resistance and activation of invasion and metastasis." (PMID 36551531, 2022). "Besides, the oncogenic role of ZNF217 has been shown in many cancers." (PMID 34899268, 2021). "Besides, ZNF217 was discovered to be an oncogene in several cancers." (PMID 32742190, 2020). "In addition to the enrichment of guides targeting TM9SF2, LAPTM4A, and genes related to sphingolipid biosynthesis, our analysis detected enrichment for guides targeting several genes associated with cancer and cell proliferation (MLLT3, TFAP4, ZNF217, and DUSP6) (35, –, 38)." (PMID 29921669, 2018). "ZNF217, a C2H2 zinc finger transcription factor, acts as a key effector in stimulating embryonic immortalisation and oncogenicity in various cancer-related processes." (PMID 36059955, 2022). "Accumulating data evidenced that deregulated ncRNA networks involving miR-200 family and lncRNA-ATB (lncRNA activated by TGF-β) are important regulators of ZNF217-driven EMT and TGF-β signaling in cancer." (PMID 36551531, 2022). "Altogether, besides assessing ZNF217/ZNF217 expression levels on tumor biopsies, assessing circulating lncRNAs/circRNAs/miRNAs targeting ZNF217 or circulating DNA methylation status at ZNF217 locus could represent a surrogate biomarker of poor prognosis or poor therapeutic response in cancer." (PMID 36551531, 2022). "Since ZNF217 can also form a complex with KDM5B, it is possible that interactions of KDM5B or other KDMs with ZNF217 occurs in other cancers." (PMID 35406676, 2022). "Altogether, this study was pioneering in demonstrating the oncogenic role of CTBP1-AS2 in cancer progression and in discovering a new CTBP1-AS2/miR-3163/ZNF217 regulatory network." (PMID 36551531, 2022). "We identified 156 focal amplifications and 69 focal deletions, in well-known oncogenes, such as ERBB2, CCNE1, KRAS, MYC, EGFR, and CDK6, and cancer-related genes such as GATA4, GATA6, CD44 and ZNF217." (PMID 31570735, 2019). "Although we have not found ZNF217 rearrangements in other AcCC cases, and we have not demonstrated ZNF217 protein expression, given its known oncogenic functions in other cancers it is intriguing to speculate a possible pathogenic role in a subset of AcCC cases." (PMID 28212443, 2017).